NDST3 (N-deacetylase and N-sulfotransferase 3)
Description:
Essential bifunctional enzyme that catalyzes both the N-deacetylation and the N-sulfation of glucosamine (GlcNAc) of the glycosaminoglycan in heparan sulfate. Modifies the GlcNAc-GlcA disaccharide repeating sugar backbone to make N-sulfated heparosan, a prerequisite substrate for later modifications in heparin biosynthesis. Has high deacetylase activity but low sulfotransferase activity.
Synonyms: HSST3
Tractability: Antibody: UniProt predicts a signal peptide or a membrane-spanning region. PROTAC: ubiquitination databases record sites on it.
Gene: Protein-coding gene on chromosome 4 (118,033,579 to 118,258,634, forward strand). Ensembl gene ENSG00000164100.
Subcellular location: Golgi apparatus membrane
Pathways (Reactome):
Metabolism: HS-GAG biosynthesis
Gene Ontology:
Molecular function: heparan sulfate N-deacetylase activity; heparan sulfate N-sulfotransferase activity; deacetylase activity; hydrolase activity; sulfotransferase activity
Biological process: heparan sulfate proteoglycan biosynthetic process; heparin proteoglycan biosynthetic process
Cellular component: Golgi apparatus; Golgi membrane
Genetic constraint (gnomAD): Loss-of-function variants: 46 observed, 84.12 expected, observed/expected ratio (o/e) 0.55, 90% interval 0.43 to 0.7. The upper end of that interval is the gene's LOEUF score, 0.7, which puts it in group 2 of 6, group 1 being the genes least tolerant of losing a copy. Missense variants: 745 observed, 1,011.2 expected, observed/expected ratio (o/e) 0.74, 90% interval 0.69 to 0.78. Synonymous variants: 317 observed, 357.12 expected, observed/expected ratio (o/e) 0.89, 90% interval 0.81 to 0.97.
Homologues: Orthologues: chimpanzee NDST3 (99% identical), macaque NDST3 (99% identical), guinea pig NDST3 (97% identical), pig NDST3 (97% identical), rabbit NDST3 (94% identical), mouse Ndst3 (93% identical), rat Ndst3 (93% identical), dog NDST3 (92% identical), Drosophila melanogaster sfl (56% identical), Caenorhabditis elegans hst-1 (42% identical), zebrafish hs3st3b1a (12% identical), zebrafish si:dkey-121b10.7 (12% identical). Paralogues in human: NDST4 (82% identical), NDST1 (71% identical), NDST2 (65% identical), HS3ST3A1 (13% identical), HS3ST4 (13% identical), HS3ST2 (13% identical), HS3ST3B1 (13% identical), HS3ST5 (11% identical), HS3ST6 (11% identical), HS3ST1 (11% identical).
Diseases named in the same sentence as NDST3 in open-access papers:
NDST3 is named in the same sentence as 16 diseases in open-access papers, as found by Europe PMC text mining. Sharing a sentence is not in itself a finding about the gene and the disease. The quoted sentences say what the papers report.
schizophrenia (8 papers, 2015 to 2024). A major psychotic disorder characterized by abnormalities in the perception or expression of reality. "In this study, we performed a comprehensive investigation of the association of NDST3 with schizophrenia and BD in the Han Chinese." (PMID 26731438, 2016). "We performed a two-stage study to investigate the association of NDST3 with the schizophrenia and BD risk in the Han Chinese." (PMID 26731438, 2016). "Recently, NDST3 was implicated as a major factor in both schizophrenia and BD pathogenesis; this finding was supported by a GWAS analysis." (PMID 26731438, 2016). "NDST3 shows enhanced expression in the brain and variants mapped to this gene have been identified as GWAS‐significant hits for multiple psychiatric traits (e.g., schizophrenia, neuroticism, worry), educational attainment and exposure to childhood maltreatment based on GWAS Catalogue results." (PMID 36777645, 2022). "In the candidate CNV regions, 26 regions had no overlaps with the common CNVs found in Asian populations and included the genes (i.e., ANTXRL, CHST9, DNM3, NDST3, SDK1, STRC, SKY) that are associated with schizophrenia and/or other psychiatric diseases." (PMID 26136833, 2015). "NDST3 and STRC are the risk genes for schizophrenia and hearing impairment that are identified by GWAS, respectively." (PMID 26136833, 2015). "NDST3 and NTNG1 were both found to be highly associated with schizophrenia in humans." (PMID 36980855, 2023). "Second, although the GWAS data indicated that the NDST3 variation possibly predisposed patients to schizophrenia and BD, to the best of our knowledge no genetic study has identified an association of NDST3 with schizophrenia and BD." (PMID 26731438, 2016). "Taken together, these results indicate that the G allele of rs11098403 is associated with a higher level of NDST3 expression, allowing NDST3 to maintain the normal neurodevelopmental processes in the hippocampus and thereby have a protective role in the development of schizophrenia." (PMID 26731438, 2016). "Five of these top eight LD-independent loci (MTHFR, PDE4B, DAOA, ARVCF, TRAM1L1/NDST3) were not located within risk loci identified in the largest schizophrenia GWA study produced by the PGC and three loci (MTHFR, DAOA, ARVCF) had never been implicated by a schizophrenia GWA study." (PMID 31455759, 2019).
bipolar disorder (4 papers, 2016 to 2024). A disorder of the brain that causes unusual shifts in mood, energy, activity levels and the ability to carry out day-to-day tasks. "Moreover, altered Ndst3 expression has been linked to shizophrenia and bipolar disorder, which may be linked to altered HS-dependent neuregulin-1 distribution and signaling." (PMID 32664575, 2020).
hepatocellular carcinoma (1 paper, 2019). A malignant tumor that arises from hepatocytes. "The overall association scores for hepatocellular carcinoma were 0.210 for HOXD9, 0.174 for NDST3, 0.111 for PZP, 0.106 for E2F8, 0.061 for ADRA2B, and 0.029 for COL15A1." (PMID 31754347, 2019).
tumor (3 papers, 2012 to 2021). "Interestingly, the NDST4 gene, located also at 4q26, and belonging to the same family than NDST3, has been identified as a possible tumour suppressor gene in CRC." (PMID 24978480, 2014). "Compared with normal kidney tissues, antibody stainings for ANKZF1, CD44, IDUA, KIF20A, PLOD2, and VCAN were high in ccRCC tumor tissues, whereas they were low for CHST6, HS6ST2, NDST3 and FBP1." (PMID 33836688, 2021).
NDST3 also shares sentences with these, for which no sentence is quoted: Anxiety (2 papers); autism (2); cancer (2); mental disorder (2); acute myelogenous leukemia (1); Alzheimer disease (1); developmental delay (1); E. coli infection (1); Hearing impairment (1); leukemia (1); neurodevelopmental disorder (1); Parkinson disease (1).